CD5 (CD5 molecule)
Diseases named in the same sentence as CD5 in open-access papers (continued):
Sharing a sentence is not in itself a finding about the gene and the disease.
Chronic lymphocytic leukemia (continued). "Chronic lymphocytic leukemia (CLL), the most common leukemia in adults, is characterized by the expansion of mature monoclonal CD5+ B cells." (PMID 29967611, 2018). "Chronic lymphocytic leukemia (CLL), the most common adult leukemia in the Western hemisphere, is characterized by gradual accumulation of mature appearing CD5+ B lymphocytes." (PMID 30263097, 2018). "Chronic lymphocytic leukemia (CLL) is a clinical and biological heterogeneous malignant disease characterized by an accumulation of monoclonal CD19+CD5+CD23+ mature small B-lymphocytes in bone marrow, blood, and lymphoid tissues." (PMID 29050251, 2017). "However, we did histologically show skin infiltration by CD-5 positive low-grade B-cell chronic lymphocytic leukemia/small lymphocytic lymphoma (B-CLL/SLL)." (PMID 28340568, 2017). "Chronic lymphocytic leukemia (CLL), the most common adult leukemia in the Western World, is characterized by the clonal expansion of CD5+ B cells in blood and peripheral tissues." (PMID 28899929, 2017). "However, skin infiltration by CD-5 positive low-grade B-cells was found, which suggested a diagnosis of chronic lymphocytic leukemia/small lymphocytic lymphoma (B-CLL/SLL)." (PMID 28340568, 2017). "Chronic lymphocytic leukemia (CLL) is the most common leukemia in Western countries and is characterized by the accumulation of CD5+ monoclonal B cells in peripheral blood and secondary lymphoid tissues." (PMID 26717038, 2016). "Chronic lymphocytic leukemia (CLL) is characterized by monoclonal proliferation of CD5 positive B cells, and this phenotype also has coexpression of CD19, CD5, and CD23 markers." (PMID 27999696, 2016). "Chronic lymphocytic leukemia (CLL) is the most common B cell leukemia in adults and is characterized by the accumulation of CD19+CD5+CD23+ B cells in the bone marrow, blood and secondary lymphoid organs." (PMID 27029059, 2016). "Chronic lymphocytic leukemia (CLL) is characterized by the clonal expansion and accumulation of mature monoclonal CD5+ B cells in the peripheral blood (PB), bone marrow (BM) and secondary lymphoid organs." (PMID 26110819, 2015). "B-cell chronic lymphocytic leukemia (CLL) is the most prevalent type of leukemia in the Western world and it manifests as a clonal expansion of CD5+, CD19+, CD23+ B cells." (PMID 25644253, 2015). "B-cell chronic lymphocytic leukemia (CLL) is a common type of leukemia, characterized by the progressive accumulation of CD5+ monoclonal B lymphocytes in peripheral blood, bone marrow and lymphoid tissues." (PMID 26305332, 2015). "Chronic lymphocytic leukemia (CLL) is a heterogeneous disease characterized by clonal proliferation and the accumulation of mature CD5+ B-cells in lymphoid tissues, bone marrow, and peripheral blood." (PMID 26050196, 2015). "Chronic lymphocytic leukemia (CLL), the most common adult leukemia in the USA, is characterized by the progressive accumulation of CD5+ B lymphocytes." (PMID 26478573, 2015). "Chronic lymphocytic leukemia (CLL) is the most prevalent adult leukemia and is characterized by an accumulation of malignant CD5+, CD19+, CD20+, CD23+ B cells that exert immunosuppressive activity." (PMID 26158860, 2015). "B-cell chronic lymphocytic leukemia (CLL) is a heterogeneous disease characterized by clonal proliferation and the accumulation of mature CD5+ B lymphocytes in the bone marrow, peripheral blood, and lymphoid tissues." (PMID 24982661, 2014). "B-cell chronic lymphocytic leukemia (CLL) is characterized by asymmetrical proliferation and apoptosis of leukemia cells co-expressing the CD5 and CD19 antigens, and several chromosomal abnormalities, including del(13q), del(11q), del(17p), and trisomy 12, are detected in most, but not all, cases." (PMID 23725032, 2013).
Chronic lymphocytic leukemia (continued). "Based on immunophenotypic grounds, MBL can be classified as chronic lymphocytic leukaemia (CLL)-like MBL, with a CD5+, CD23+ and CD20low phenotype representing the most common subgroup (∼ 75/80% of MBL), atypical-CLL (CD5+, CD20bright) and CD5− MBL." (PMID 23285188, 2012). "Immunohistochemically, small lymphocytic lymphoma expresses IgM/IgD, CD20, CD22, CD5, CD19, CD79a, CD23, CD43 and CD11c." (PMID 22333190, 2012). "SLL is the nodal counterpart of chronic lymphocytic leukemia (CLL), and the tumor B-cells express dually CD5 and CD23 in addition to pan-B-cell antigens, CD19, and CD20." (PMID 23162567, 2012). "Assessment of blood by flow cytometry and pericardial biopsy by immunohistochemistry revealed CD5 (+) and CD20 (+) lymphocytes in both tissues, demonstrating this to be an unusual manifestation of early stage chronic lymphocytic leukemia." (PMID 20684780, 2010). "Coexpression of CD5, CD23, and LEF1 distinguishes chronic lymphocytic leukaemia from MALT lymphoma, although occasional expression of CD5 or CD23 may be seen in MALT lymphoma." (PMID 40831827, 2025). "The cells in SMZL are CD5/CD10-negative, which can make the diagnosis challenging, given the differential for CD5/CD10-negative lymphomas includes hairy cell leukemia, lymphoplasmacytic lymphoma (LPL), marginal zone lymphoma, and CD5-chronic lymphocytic leukemia." (PMID 40271287, 2025). "Chronic lymphocytic leukemia (CLL) and small lymphocytic lymphoma (SLL), which are considered to be the same disease, are forms of non-Hodgkin lymphoma that are characterized by clonal proliferation and accumulation of small CD5-positive B cells." (PMID 39586984, 2025). "Briefly, the approach requires FC combinations with sufficient differences in antigen expression between normal and small abnormal populations (for example, expression of CD5 and decreased CD20 in the case of chronic lymphocytic leukemia/small lymphocytic lymphoma)." (PMID 40075660, 2025). "For example, CD5 (−) can rule out small lymphocytic lymphoma, Cyclin D1 (−) can rule out mantle cell lymphoma." (PMID 38640287, 2024). "CD5 negativity is important to rule out B-cell chronic lymphocytic leukemia or mantle cell lymphoma." (PMID 38534887, 2024). "Chronic Lymphocytic Leukemia (CLL) is an indolent malignancy characterized by the accumulation of quiescent, immunologically dysfunctional mature B cells which are CD5 positive and that fail to undergo apoptosis, leading to leukocytosis and absolute lymphocytosis, lymphadenomegaly, and splenomegaly." (PMID 38920977, 2024). "Chronic lymphocytic leukemia (CLL), the most frequent type of leukemia in adults, is a lymphoproliferative disorder that is characterized by the expansion of monoclonal, mature CD5 + CD23 + B cells in the peripheral blood, secondary lymphoid tissues, and bone marrow." (PMID 37946029, 2024). "In addition, the over-expression of CMC4 (also known as MTCP1), as a favorable prognosis gene in our model, was discordantly reported to produce clonal CD5+/CD19+ leukemia in mice, which was thought to be a chronic lymphocytic leukemia driving gene." (PMID 36816541, 2023). "A liquid reagent drop-in of CD23-ECD in the DURAClone RE CLB panel could further confirm B-cell CLL and discern B-cell CLL from other CD19/CD5 co-expressing target populations." (PMID 36483322, 2022). "Chronic lymphocytic leukemia (CLL) is a lymphoproliferative malignancy that is categorized by the production and accumulation of CD5+ monoclonal B cell lymphocytes, commonly in the spleen, bone marrow, and peripheral blood; these are morphologically mature lymphocytes with abnormal immune function." (PMID 36290811, 2022). "Furthermore, the small lymphatic cells of the dense B-cell region showed a co-expression of CD5 and CD23, leading altogether to the phenotype of a chronic lymphatic leukaemia (CLL)/a small lymphocytic lymphoma (SLL)." (PMID 35448198, 2022).
Chronic lymphocytic leukemia (continued). "CLL is regarded as similar to small lymphocytic lymphoma (SLL) by the World Health Organization (WHO) because they share several clinical features including immunophenotype (CD5+/CD19+ and CD5+/CD23+) and morphology; however, they differ with regard to the site of B-cell proliferation." (PMID 36498556, 2022). "The under-expression of CD81, CD79b, and positive CD43 and ROR1 expression, noted in the DURAClone CLB panel specifically assists in distinguishing B-cell CLL from mantle cell lymphoma and other CD5 negative B-cell LPDs." (PMID 36483322, 2022). "Flow cytometry revealed expression of CD5 and CD23, consistent with chronic lymphocytic leukemia." (PMID 31827949, 2019). "In a mouse model of chronic lymphocytic leukemia (CLL), characterized by the abnormal expansion of CD5+ B-cells in bone marrow and secondary lymphoid organs, there is increased RA signaling activity by leukemic cells with accumulation of ATRA in the stromal microenvironment as result." (PMID 31805753, 2019). "Aside from the lack of CD5 expression, the morphologic and immunophenotypic findings were consistent with chronic lymphocytic leukemia/small cell lymphoma." (PMID 30755837, 2018). "Using flow cytometric immunophenotyping, the peripheral lymphocytes were positive for CD5, CD20, and CD23 (with expression of IgM and IgD lambda) and negative for CD38; this profile was consistent with a diagnosis of chronic lymphocytic leukemia (CLL; Matutes score: 5)." (PMID 28082975, 2016). "Chronic lymphocytic leukemia (CLL) is one of the most common types of adult leukemia, and is characterized by a typical immunophenotype of CD19, CD20, CD23 with co-expression of the pan T-cell marker CD5." (PMID 24130782, 2013). "Chronic lymphocytic leukemia (CLL) is characterized by the gradual accumulation of small mature B-cells, non proliferating cells and B-cell surface markers such as CD19, CD20 in addition to CD5 in the patient." (PMID 20226080, 2010). "The negative CD5, CD23, and CD200 may exclude the diagnosis of chronic lymphocytic leukemia/small cell lymphoma, and the negative CD5, Cyclin D1, FMC7, and SOX-11 can exclude the possibility of mantle cell lymphoma." (PMID 38335376, 2024). "Chronic lymphocytic leukaemia/small lymphocytic lymphoma (CLL/SLL) and mantle cell lymphoma (MCL) are two lymphoid neoplasms characterized by the clonal expansion of mature small CD5+ B cells that may involve the bone marrow, blood, lymphoid tissues, and extranodal sites." (PMID 36454275, 2023). "Chronic lymphocytic leukaemia (CLL) is a chronic lymphoproliferative disorder characterised by accumulation of mature monoclonal B lymphocytes, more than 5000 per microlitre in peripheral blood, positive for immunophenotype marker (CD5+ and CD23+) and/or the involvement of lymph nodes." (PMID 36900108, 2023). "Chronic lymphocytic leukemia (CLL) is the most frequently diagnosed subtype of leukemia in adults and is a lymphoproliferative disorder that is characterized by the expansion of monoclonal, mature CD5+ CD23+ B cells in the peripheral blood, secondary lymphoid tissues, and bone marrow." (PMID 34947813, 2021). "Chronic lymphocytic leukemia (CLL) is the most common adult leukemia in western countries and is characterized by the gradual accumulation of mature B lineage-specific markers such as CD19, CD20, and CD23 and additionally the CD5 antigen in lymphoid tissues, bone marrow, and peripheral blood (PB)." (PMID 32775467, 2020). "Chronic lymphocytic leukemia (CLL), the most common leukemia in adults in western countries, is characterized by the progressive accumulation of mature-appearing clonal B cells expressing CD5, CD23, and CD19 surface markers in the blood, bone marrow and secondary lymphatic tissues." (PMID 31681329, 2019).
Chronic lymphocytic leukemia (continued). "The dependence of malignant B cells on some types of myeloid cells for continued survival is not unprecedented, as CD5+ B1-derived chronic lymphocytic leukemia (CLL) cells are highly dependent on nurse-like cells with M2 TAM phenotypes for mediation of growth and survival." (PMID 29868471, 2018). "A 68-year-old male was first diagnosed with B-cell chronic lymphocytic leukemia (B-CLL) in July 2006, based on incidental finding of lymphocytosis, blood film morphology, and the typical lymphocyte surface markers with positive CD19, CD5, CD23, and weak expression of surface lambda." (PMID 23533846, 2012). "B-cell Chronic Lymphocytic Leukemia (B-CLL) is characterized by the clonal expansion and accumulation of CD19+ CD5+ malignant -though quiescent- lymphocytes in the blood, the bone marrow and the lymphoid tissues." (PMID 24212774, 2011). "Comparison of key immunophenotypic markers (CD5, CD10, CD23, CD25, CD103, cyclin D1) to differentiate chronic lymphocytic leukemia (CLL), mantle cell lymphoma (MCL), follicular lymphoma (FL), hairy cell leukemia (HCL), and splenic diffuse red pulp lymphoma (SDRPL)." (PMID 40585661, 2025). "For example, chronic lymphocytic leukemia (CLL) is an expansion of malignant CD5+CD19+ B cells, yet the non-malignant T cells play just as large of a role in disease presentation and etiology." (PMID 28512625, 2017). "The immunophenotypic profile (CD5-negative, CD10-negative, kappa-restricted) excluded chronic lymphocytic leukemia/small lymphocytic lymphoma (typically CD5-positive) and follicular lymphoma (typically CD10-positive)." (PMID 41531558, 2025). "Chronic lymphocytic leukemia (CLL) is a lymphoid malignancy characterized by the accumulation and proliferation of nonfunctional and monoclonal small CD5/CD19/CD-20/CD23-positive lymphocytes in the blood, bone marrow, and lymphoid tissues." (PMID 25093123, 2014). "In particular, it is usually negative for CD5, which helps differentiate EMZL from MCL and chronic lymphocytic leukemia." (PMID 23691402, 2013). "Additionally, cells classically stain positive for the B‐cell associated antigens CD20 and CD79a, with negative staining for CD5, CD10, and CyclinD1 to rule out small lymphocytic lymphoma, follicular lymphoma, and mantle cell lymphoma, respectively." (PMID 40236309, 2025). "Discriminating WM from chronic lymphocytic leukemia (CLL), mantle cell lymphoma (MCL), and follicular lymphoma involves noting the presence of CD19, CD20, CD22, CD79α, and CD138 cell expression and lack of CD5, CD10, and CD23." (PMID 36232447, 2022). "Moreover, CD5, CD23, CD10, CD21, BCL-6, and Cyclin D1 were all negative, which could exclude the diagnosis of small lymphocyte lymphoma, follicular lymphoma, and mantle cell lymphoma." (PMID 33585230, 2020).
lymphoma (134 papers, 1991 to 2026). A malignant (clonal) proliferation of B- lymphocytes or T- lymphocytes which involves the lymph nodes, bone marrow and/or extranodal sites. "Bovine leukemia virus (BLV) is an exogenous retrovirus that causes enzootic bovine leukosis (EBL), a lymphoma of infected CD5+ IgM+ B cells, in cattle." (PMID 35632737, 2022). "The aberrant CD21 expression was significantly more frequent in TZL than in T-NOS lymphomas (p < 0.001), whereas the loss of CD5 and CD44 was more frequent in the latter (p < 0.001 and p = 0.004, respectively)." (PMID 35448684, 2022). "Since human U-CLL is TC+ZAP70+CD5+, we further compared TC– and TC+Tg ATAμκTg mice by microarray analysis, to determine why TC+Tg mice showed lymphoma/leukemia development in middle age instead of old aged." (PMID 38570827, 2024). "So far, there have been a few of phase I studies (NCT03081910, NCT04689659, NCT04004637) in regard to the CAR-T cells targeting CD5 or CD7 to treat relapsed/refractory T-lymphocytic leukemia/lymphoma, but with tumor recurrence." (PMID 39462383, 2024). "When ATA μκTg generation in mice, ATA B cells are the neonate generated CD5+ B cells in B-1, and in the middle age, CD5+ can be down or continuously CD5+, then, old aged CLL/lymphoma generation with increased CD11b in TC–ZAP70–CD5– or TC–ZAP70+CD5+." (PMID 38570827, 2024). "Similar to the results of this study, the impact of CD5 positivity in B-cell NHL is largely dependent on the subtype of lymphoma." (PMID 39410047, 2024). "Large T-cells were <4% in reactive lymph nodes and >4% in lymphomas and showed a higher CD5 MFI in lymphomas (if expressed) compared to reactive lymph nodes." (PMID 37368760, 2023). "The patients in the CD5-/CD10-lymphoma group had lower hemoglobin content compared with the other three patient groups." (PMID 36624655, 2023). "The current study presents the clinicopathological features, diagnostic approach, and clinical outcomes of this HIV-related lymphoma and highlights the importance of the early diagnosis of CD5-positive DLBCL." (PMID 36827036, 2023). "We analyzed the peripheral blood and BM samples of 131 patients with B-cell CLDs (including 91 CLL, 15 atypical CLL, 14 MCL, and 11 CD5-/CD10-lymphoma patients) from April 2018 to April 2019, using a panel of specific markers by flow cytometry." (PMID 36624655, 2023). "Large T-cells were ≤4% in reactive lymph nodes and >4% in T-cell lymphomas and showed higher CD5 expression in lymphomas compared to reactive lymph nodes." (PMID 37368760, 2023). "Four clinical trials (phase I) use CAR-T to target CD5 for T-cell leukemia/lymphoma/T-cell malignancy therapy." (PMID 37108359, 2023). "Platelet count was lower in the atypical B-CLL group compared with the B-CLL, MCL, and CD5-/CD10-lymphoma groups (p = 0.013)." (PMID 36624655, 2023). "In this study, we assessed a total of 131 patients with different B-cell CLDs, including B-CLL, atypical B-CLL, MCL, and CD5-/CD10-lymphoma, for a panel of B-cell-specific markers viz CD5, CD20, CD22, CD23, and FMC-7." (PMID 36624655, 2023). "After receiving induction therapy, he developed convulsions, and lymphoma cells expressing CD5-positive and CD10-positive were detected in cerebrospinal fluid (CSF)." (PMID 35186599, 2022). "We quantitated the cytotoxic activity in a 1:1 effector-to-target ratio on lymphoma cells (CD5+ CD7‒) from three different patients and found that all CAR constructs were highly effective to eliminate lymphoma cells compared to NK cells not expressing a CAR." (PMID 35158792, 2022). "When considering TZL and T-NOS lymphomas, a significantly different prevalence of specific phenotypic aberrancies was found: aberrant CD21 expression was more common in TZL, whereas loss of CD5 and CD44 were more common in T-NOS." (PMID 35448684, 2022). "The genetic alterations, including the SNVs, small indels, splice variants, CNVs, and structural variations (SVs) of CD5+ and CD5- DLBCL cases, were determined by a lymphoma-related 475-gene panel." (PMID 36081566, 2022).